RNU6-631P (RNA, U6 small nuclear 631, pseudogene)
Gene: Small nuclear RNA gene on chromosome 15 (21,866,210 to 21,866,316, reverse strand). Ensembl gene ENSG00000200790.
Homologues: Orthologues: macaque U6 (92% identical), macaque U6 (90% identical), guinea pig U6 (79% identical), dog U6 (76% identical), pig U6 (68% identical). Paralogues in human: RNU6-749P (100% identical), U6 (100% identical), RNU6-1021P (99% identical), RNU6-286P (98% identical), U6 (98% identical), RNU6-127P (93% identical), RNU6-1239P (93% identical), RNU6-1268P (93% identical), RNU6-473P (93% identical), RNU6-617P (93% identical), RNU6-816P (93% identical), RNU6-848P (93% identical), and 1288 more.